APOC3 (apolipoprotein C3)
Diseases named in the same sentence as APOC3 in open-access papers (continued):
Sharing a sentence is not in itself a finding about the gene and the disease.
tumor (12 papers, 1999 to 2024). "In a study of East Asian breast patients, researchers found that lower expressions of APOA5 and APOC3 were associated with higher ESTIMATE immune scores, which means a large number of tumor-infiltrating immune cells." (PMID 35692496, 2022). "Mechanistically, our discovery analysis indicated that expressions of APOA1, APOC3, and APOA5 are inversely associated with tumor-infiltrating immune cells, and we proposed that they exert an immunomodulatory effect on the tumor microenvironment." (PMID 34226567, 2021). "Lower APOA1, APOC3, and APOA5 expressions were associated with higher ESTIMATE immune scores, indicating an abundance of tumor-infiltrating immune cells." (PMID 34226567, 2021). "The lower levels of APOA1, APOC3, and APOA5 expression were associated with higher ESTIMATE immune scores, which indicated an abundance of tumor-infiltrating immune cells." (PMID 34226567, 2021). "By evaluating the radiology imaging of these two patients, we observed not only negative association between tumor size and APOC3 protein levels in the patients, but also the appearance some new metastases." (PMID 38719824, 2024). "APOC3 was mainly expressed in pit mucous cells, while SNCG expression was enriched in myofibroblasts and tumor cells." (PMID 37100457, 2023). "In contrast, the lower expression levels of APOC3 and SNCG in tumor, together with their protective roles in the prognostic signature, have further revealed their potential suppressor functions in GC." (PMID 37100457, 2023). "Augmented APOA1 reflects its potential role in driving therapeutic resistance and disease progression by reprogramming the lipid metabolic network of tumor cells; APOB, APOC3, and APOH may function like APOA1." (PMID 39318189, 2024). "In detail, for P2, APOC3 protein level showed the negative correlation between tumor size of retroperitoneal lymph nodes, porta hepatis, and right pleural metastases." (PMID 38719824, 2024). "More importantly, the tumor size of two metastases showed the negative correlation with the APOC3 protein level during the DBT." (PMID 38719824, 2024). "A study found that APOC1, APOC2, APOC3, and APOC4 were expressed differently in tumor and non-tumor tissues in hepatocellular carcinoma." (PMID 38067270, 2023).
heart disease (8 papers, 2008 to 2025). "Certain genetic mutations in APOC3 can lead to lower triglyceride levels and reduce the likelihood of heart disease." (PMID 39286687, 2024). "Loss of function variants of APOC3 can additionally result in hyperalphalipoproteinaemia, which may have an influence on heart disease." (PMID 32489792, 2020). "This study presented evidence that reducing APOC3 activity has a protective impact on heart disease." (PMID 39286687, 2024). "The 11q23-24 human genome location is well known for a cluster of genes (APOA1, APOC3, APOA4, and APOA5), which effect the lipid levels as well as is associated with DM and heart disease." (PMID 19038053, 2008).
kidney disease (7 papers, 2014 to 2025). "Since APOC3 silencing reduced blood glucose, and improved glycemia is associated with improved kidney disease, we tested the effect of APOC3 silencing in a model in which APOC3 ASO does not reduce blood glucose." (PMID 38743496, 2024). "A report that APOC3 can be post-translationally guanidinylated and that the mass-signal intensity of guanidinylated APOC3 associated with kidney disease and CVD outcomes requires further study." (PMID 37972731, 2024). "Many studies have shown that kidney disease is related to the expression of APOC3." (PMID 39684468, 2024). "For example, we observe that tubular cells contain lipid droplets, which is reversed by APOC3 ASO treatment, and defective lipid metabolism in tubular epithelial cells has been shown to contribute to kidney disease." (PMID 38743496, 2024).
neurological disease (3 papers, 2023 to 2025). "In a previous study, significantly higher levels of APOC3 were detected in the CSF and serum of GBS patients compared to other neurological diseases and healthy control groups." (PMID 38143756, 2023). "Additionally, our study revealed significantly higher expression of APOC3 in the CSF and serum of GBS patients compared to other neurological disease groups and healthy individuals undergoing physical examination." (PMID 38143756, 2023).
APOC3 also shares sentences with these, for which no sentence is quoted: pancreatic cancer (4 papers); renal failure (4); retinopathy (4); angina pectoris (3); aortic stenosis (3); carotid atherosclerosis (3); colon cancer (3); familial chylomicronemia (3); hyperalphalipoproteinemia (3); lipodystrophy (3); neuropathy (3); systemic lupus erythematosus (3); Abdominal obesity (2); antiphospholipid syndrome (2); calcification (2); cognitive decline (2); diabetic retinopathy (2); familial partial lipodystrophy (2); genetic disorder (2); hepatitis B (2); Hyperinsulinemia (2); Liver Dysfunction (2); metastatic disease (2); mixed hyperlipidemia (2); Nephropathy (2); nephrotic syndrome (2); nonalcoholic steatohepatitis (2); secondary hyperparathyroidism (2); systemic amyloidosis (2); transient ischemic attack (2).
A further 97 diseases each share a sentence with APOC3 in 2 papers or fewer.